ACSL1 (acyl-CoA synthetase long chain family member 1)
Diseases named in the same sentence as ACSL1 in open-access papers (continued):
Sharing a sentence is not in itself a finding about the gene and the disease.
liver cancer (12 papers, 2014 to 2023). An epithelial or non-epithelial malignant neoplasm that arises from the liver. "The authors propose a mechanistic link between maternal high-fat diet and the development of liver cancer through the downregulation of two genes, Acyl-CoA synthetase long chain family member 1 (Acsl1) and Aldehyde dehydrogenase family member 2 (Aldh2)." (PMID 35833105, 2022). "Liver cancer cells have shortcomings in the study of lipid metabolism, so it is more meaningful to adopt healthy human liver cells as the vector of ACSL1 gene and triglyceride metabolism and mechanism." (PMID 32218693, 2020). "Upregulation of ACSL1 has been observed in various cancer types, including breast cancer, colon cancer, and liver cancer." (PMID 31681299, 2019). "Interestingly, aspirin down-regulates ACSL1 expression in liver cancer cells and suppresses abnormal lipid metabolism via inhibition of NFκB-ACSL1 signaling." (PMID 31681299, 2019). "In addition, miR-205 blocks the lipogenesis in liver cancer and anti-miR-205 promotes the increase of triglyceride by ACSL1." (PMID 27171439, 2016). "ACSL1, which is miR-205-targeted, might contribute to aberrant lipid metabolism in liver cancer." (PMID 36483029, 2022). "The DSS analysis results displayed that liver cancer patients with high expression of ATF3, ACSL1, and LPIN1 exhibited significantly longer DSS." (PMID 37580343, 2023). "By analyzing RNA-seq data from TCGA and GTEx, we discovered that ATF3, ACSL1, LPIN1, and DDR2 were significantly downregulated while DDIT3 was upregulated in liver tumor compared with normal tissues, implying that these five genes might be associated with liver cancer." (PMID 37580343, 2023). "The data revealed that the expression level of HAAO in liver cancer is negatively correlated with ferroptosis‐resistant genes including SLC7A11, SLC3A2, and ACSL3, whereas positively correlated with ferroptosis‐sensitive gene ACSL1." (PMID 36627132, 2023). "The downregulation of miR-205 mediated by HBx remarkably increases the expression levels of acyl-CoA synthetase long-chain family member 1 (ACSL1), and its metabolite triglyceride levels are remarkably increased in HBx-induced liver cancer tissues, as shown in an HBx transgenic mice model." (PMID 25364579, 2014).
Sepsis (11 papers, 2019 to 2025). Sepsis is defined as life-threatening organ dysfunction caused by a dysregulated host response to infection. "Conclusions from the literature and publicly available transcriptome data suggest that ACSL1 is probably involved in neutrophil inflammasome activation during sepsis." (PMID 39262873, 2024). "Previous studies have shown that ACSL1 plays a proinflammatory role in monocytes/macrophages and neutrophils in sepsis." (PMID 39262873, 2024). "Apart from macrophages, ACSL1 was also observed to be highly expressed in neutrophils in fatal sepsis." (PMID 34960652, 2021). "Expression of transcripts comprising this aggregate is generally restricted to neutrophils and robustly increased during sepsis (e.g. as we have described in detail earlier for ACSL1, another transcript belonging to this aggregate)." (PMID 32736569, 2020). "The actual role played by ACSL1 in sepsis and its contribution to the pathophysiology of this condition remains to be defined." (PMID 31681299, 2019). "In order to draw inferences on the possible role played by ACSL1 in sepsis, context was obtained by conducting a background literature review." (PMID 31681299, 2019). "With the increase in ACSL1 abundance confirmed in multiple independent sepsis datasets, the next step consisted in interrogating the literature for current knowledge about its role in this setting." (PMID 31681299, 2019). "Another take on a potential mechanisms regulating ACSL1 expression originates from the fact that lipid metabolism is frequently deregulated during sepsis, characterized by changes in cholesterol, HDL and apolipoproteins in plasma of septic patients." (PMID 31681299, 2019). "A potential role for the long-chain acyl-CoA synthetase family member 1 (ACSL1) in the immunobiology of sepsis was explored during a hands-on training workshop." (PMID 31681299, 2019). "Follow on work should permit to characterize more precisely the role of ACSL1 in neutrophils and sepsis." (PMID 31681299, 2019). "The abundance of ACSL1 transcripts is increased in sepsis in a wide range of study settings, but literature describing mechanisms regulating its expression or its role in this context is lacking." (PMID 31681299, 2019). "Multiple researches have confirmed an increased transcript abundance of ACSL1 during sepsis." (PMID 41424725, 2025). "ACSL1 was considered as an indicator of severe sepsis, in addition to ACSL4." (PMID 34960652, 2021). "Taking the sepsis-like symptoms of COVID-19 patients into consideration, ACSL1 may serve as an intriguing therapeutic target to restrict cytokine storm in COVID-19." (PMID 34960652, 2021). "Taken together, inferences that could be drawn based on both profiling of the literature and transcript co-expression analysis confirm a likely role of ACSL1 in driving inflammasome-mediated release of pro-inflammatory factors by neutrophils during sepsis." (PMID 31681299, 2019). "Increase in ACSL1 transcript abundance during sepsis was confirmed in several independent datasets." (PMID 31681299, 2019). "Because TLR4 activation by ligands such as LPS was one of the dominant causes for severe sepsis in bacterial infection, and TLR4 inhibition by TAK-242 alleviated fatal infection by MHV-A59, we reasoned that ACSL1 upregulation may be the consequence of TLR4 signaling activation." (PMID 34960652, 2021). "Importantly, gene expression of PPARα and downstream genes was also increased after pemafibrate in livers of CLP mice 24 h post‐sepsis initiation, with many genes reaching expression levels close to those seen in vehicle‐treated sham mice (only Acsl1 and Slc25a20 are shown, Fig EV3C and D)." (PMID 31916705, 2020). "Querying the ACSL1 literature also confirmed the absence of reports associating ACSL1 with sepsis." (PMID 31681299, 2019). "Based on literature as well as inferences from co-expression analyses in other literature, ACSL1 and ACSL4 expression levels were significantly higher in fatal sepsis cases." (PMID 39262873, 2024).
Sepsis (continued). "The Venn diagram shows that a total of eight overlapping genes were discovered between ACSL4 co-expression genes and sepsis, including GK, CLEC4E, ACSL1, TGFBR3, ADAM9, AZI2, BCAT1, and CYP1B1." (PMID 39262873, 2024). "Inferences drawn from both the literature (via indirect associations) and public transcriptome data (via correlation) point to the likely participation of ACSL1 and ACSL4, another family member, in inflammasome activation in neutrophils during sepsis." (PMID 31681299, 2019). "Furthermore, available clinical data indicate that levels of ACSL1 and ACSL4 induction was significantly higher in fatal cases of sepsis." (PMID 31681299, 2019). "And that a role for ACSL1 in neutrophil immunobiology has been described, but not in the context of sepsis." (PMID 31681299, 2019). "- Third, that an increase in ACSL1 expression has not been reported in the literature in the context of sepsis to date." (PMID 31681299, 2019).
colon cancer (10 papers, 2015 to 2025). "SNPs in the 3′ UTR of the human ACSL1 gene influence its expression and thus results in poor clinical outcome in colon cancer patients." (PMID 37509093, 2023). "In colon cancer cells, a cooperative metabolic network comprising overexpression of the Acyl-CoA synthetases ACSL1, ACSL4 and the related enzyme SCD induces EMT and increases cellular migration and invasion." (PMID 34073989, 2021). "ACSL1 has been recently involved in lipid metabolism alterations in cancer, including in a screening in colon cancer of lipid metabolism-related genes recently conducted in our research group." (PMID 26451612, 2015). "The combined analysis of these 4 genes, ABCA1, ACSL1, AGPAT1 and SCD, constitutes a metabolic-signature (ColoLipidGene) able to accurately stratify stage II colon cancer patients with 5-fold higher risk of relapse with strong statistical power in the four independent groups of patients." (PMID 25749516, 2015). "Co-expression analysis revealed that ACSL1 was coexpressed with MYBPH, PTPRE, PFKFB3, SOCS3 in colon cancer and with LRRFIP1, TSC22D1 in lung cancer." (PMID 27171439, 2016). "For this purpose we generated human colon cancer stable cell lines overexpressing either ACSL1, ACSL4 or SCD (ACSL1 cells, ACSL4 cells, and SCD cells, respectively) or the three genes simultaneously (x3 cells), transducing the DLD-1 CRC cell line with specific lentiviruses." (PMID 26451612, 2015). "Collectively, these results imply that ACSL1, ACSL4 and SCD increased expression might act as a marker of poor prognosis which contributes to reduced disease free survival of colon cancer patients." (PMID 26451612, 2015). "The model including the four LMGs (ABCA1, ACSL1, AGPAT1 and SCD) is proposed as a prognostic marker of colon cancer with stage II, but not effective in all stages of colon cancer." (PMID 37055842, 2023). "Also, ACSL1 and ACSL4 overexpression increases migration and invasion in colon cancer cells but not proliferation and contribute to a non‐Warburg advantageous energetic status of invasive colon cancer cells." (PMID 33030783, 2020).
prostate carcinoma (10 papers, 2020 to 2024). A carcinoma that arises from epithelial cells of the prostate gland. "Changes in FA metabolism enzymes have also been reported in prostate cancer, where elevated expression of ACSL1 was associated with serum acyl-CoA levels, which promoted cancer progression via augmented β-oxidation and lipogenesis." (PMID 35954376, 2022). "Prostate cancer cells use β-oxidation of fatty acids as their main energy source, and ACSL1 promotes prostate cancer progression by increasing lipogenesis and FAO." (PMID 38783346, 2024). "A role for ACS in TAG formation has been shown in prostate cancer cells where knockdown of ACSL1 resulted in reduced TAG levels." (PMID 36927839, 2023). "The knockdown of ACSL1 inhibited the cell cycle, and it suppressed the proliferation and migration of prostate cancer cells in vitro and the growth of prostate xenograft tumors in vivo." (PMID 36364557, 2022). "ACSL1 knock-down has been shown to result in decreased prostate cancer cell migration and proliferation in vitro and inhibited the growth of prostate cancer xenograft tumours in vivo." (PMID 35954376, 2022). "Additionally, the lncRNA SNHG7/miR‐449a/ACSL1 axis in thyroid cancer and the circPDHX/miR‐497‐5p/ACSL1 axis in prostate cancer have been identified to promote cancer cells’ proliferation and migration." (PMID 37939296, 2024).
atherosclerosis (9 papers, 2017 to 2025). A disease characterized by the build-up of fatty material and calcium deposition in the arterial wall resulting in partial or complete occlusion of the arterial lumen. "Consistent with ACSL1 links to cardiovascular and metabolic diseases in humans, analysis of genome-wide association studies found intronic SNPs in ACSL1 associated with atherosclerosis and type-2 diabetes." (PMID 36054206, 2022). "In light of the present findings, increased macrophage death could have contributed to our previous findings of smaller early lesions of atherosclerosis in diabetic mice with myeloid cell ACSL1-deficiency, a condition associated with increased IFN stimulation." (PMID 39675509, 2025). "Genes IRAK4, HDAC9, ACSL1 and APPL159 are recently reported as atherosclerosis causing genes in T2DM patients." (PMID 28761062, 2017). "Prior studies have shown that macrophage-specific expression of Acsl1 plays a pivotal role in exacerbating atherosclerosis in diabetic mice, and the adoptive transfer of Acsl1−/− macrophages may represent a potential therapeutic strategy for atherosclerosis." (PMID 39329770, 2024). "miR-146a can also regulate lipid droplet formation by targeting ACSL1, which may be a potential biomarker and therapeutic target for atherosclerosis." (PMID 36513974, 2022). "Loss of ACSL1 in IFN-I stimulated myeloid cells enhances apoptosis and secondary necrosis in vitro, especially in the presence of increased saturated fatty acid load, and in a mouse model of atherosclerosis associated with IFN overproduction, resulting in larger lesion necrotic cores." (PMID 39675509, 2025). "On the other hand, our study shows that the Pep_A6 vaccine can regulate the expression of liver genes such as Fitm2, Gk, Plin2, Acsl1, Fatp1, and Acot4, thereby lowering serum LDL-C levels and hepatic lipid accumulation while improving atherosclerosis." (PMID 39329770, 2024).
COVID-19 (8 papers, 2021 to 2025). A disease caused by infection with severe acute respiratory syndrome coronavirus 2. "As a result of intersecting 73 COVID-19-related IS genes with ferroptosis genes, we obtained two ferroptosis genes (ACSL1, CREB5) that were relevant to COVID-19-related IS." (PMID 37606960, 2023). "Finally, three genes associated with immunity (B4GALT5, CRISPLD2, F5) and two genes associated with ferroptosis (ACSL1, CREB5) were identified up-regulated in COVID-19-related IS." (PMID 37606960, 2023). "In CD14+ monocytes, HIF-1 signaling may regulate LDHA, ALDOA, TIMP1, ELOB and IFNGR2, and PPAR signaling may regulate UBC, RXRA, DBI and ACSL1 in COVID-19 patients." (PMID 33936072, 2021). "The role of ACSL1 in COVID-19 and IS remains unclear but may relate to ferroptosis." (PMID 39469068, 2024). "While ARG1 and ACSL1 were upregulated in both diseases, IQGAP1 was downregulated in COVID-19 but upregulated in IS." (PMID 39469068, 2024). "The lowest number of the common DEGs was observed between COVID-19 and IS, including ARG1, ACSL1 and IQGAP1." (PMID 39469068, 2024). "Indeed, different proteins associated to viral infection like the Long-chain Acyl-CoA synthetase 1 (ACSL1), Calpain-5 (CAPN5) or Syntaxin 10 (STX10), appeared down-regulated in ECFCs after stimulation with the serum of COVID-19 positive individuals." (PMID 37063416, 2023).
lung carcinoma (8 papers, 2016 to 2025). "An in silico study also suggested that high ACSL1 expression was associated with worse survival in lung cancer patients, and ACSL3 overexpression was associated with worse survival in patients with melanoma." (PMID 33030783, 2020). "ACSL1 is linked to poorer prognosis in BC but better prognosis in lung cancer." (PMID 40337509, 2025). "ACSL1 had three variants, and the composition of ACSL1 variants between the NHBE and lung cancer cell lines was different." (PMID 38539505, 2024). "The bioinformatics prediction of potential role of ACSL1 from Oncomine and PrognoScan in colorectal and lung cancer is supported by the in vitro assay." (PMID 27171439, 2016). "In contrast, increase of oncogenic property was observed in lung cancer cell line by attenuating ACSL1." (PMID 27171439, 2016). "As for lung cancer, ACSL1 was coexpressed with leucine rich repeat (in FLII) interacting protein 1 (LRRFIP1) and TSC22 domain family member 1 (TSC22D1)." (PMID 27171439, 2016). "Taken together, our data suggest that ACSL1 may be a potential diagnostic marker for lung ADC, and that ACSL1, ACSL4, and ACSL5 may be involved in lung cancer differentiation." (PMID 38539505, 2024). "The ACSL1-coexpressed genes were identified from colorectal and lung cancer datasets respectively." (PMID 27171439, 2016). "In addition, the GO Process demonstrates the diverse effects of ACSL1 on colorectal and lung cancer." (PMID 27171439, 2016). "The mRNA data from KM Plotter showed that ACSL1 and ACSL5 were favorable prognostic markers in lung cancer." (PMID 38539505, 2024). "The results from the Western blot analysis indicate that normal bronchial epithelial cells and lung cancer cells may have different splice variants of ACSL1; however, it is not yet clear whether or to which extent this discrepancy may cause any biological impact on tumor cells." (PMID 38539505, 2024). "We found that, compared to normal human bronchial epithelial (NHBE) cells, ACSL1, ACSL4, and ACSL6 were highly expressed, while ACSL3 and ACSL5 were lost in the majority of lung cancer cell lines." (PMID 38539505, 2024). "Compared to the NHBE cells, the mRNA expression of ACSL1, ACSL3, and ACSL6 was downregulated in all the lung cancer cell lines." (PMID 38539505, 2024). "Different from lung cancer, ACSL1‐5 is highly expressed in ATI of COPD as the representative of lung chronic inflammation, ACSL1 and 3 in ATI and basal cells of IPF as fibrosis and ACSL4 in ATI cells of SSC as a systemic immune disorder." (PMID 36639836, 2023). "According to the results from the Oncomine and PrognoScan databases, ACSL1 is modestly expressed in lung carcinoma, negatively correlated with fatty acid transport protein 2 (FATP2), and the interaction between ACSL1 and FATP2 promotes non-small-cell lung cancer (NSCLC) cell progression." (PMID 38539505, 2024). "Taken together, the data suggest that ACSL1 may be a biomarker for lung ADC, and ACSL1, ACSL4, and ACSL5 may be involved in lung cancer differentiation, and TC, in combination with chemotherapy or EGFR-TKIs, may help patients overcome drug resistance." (PMID 38539505, 2024). "In human lung cancer cells, we found that the proteins of ACSL1, ACSL4, and ACSL6 were highly expressed in most of the lung cancer cell lines observed, while the proteins of ACSL3 and ACSL5 were lost in the majority of the lung cancer cell lines, compared to the NHBE cells." (PMID 38539505, 2024).
Insulin resistance (6 papers, 2014 to 2024). Increased resistance towards insulin, that is, diminished effectiveness of insulin in reducing blood glucose levels. "The rs9997745 SNP in ACSL1 we identified has been previously associated with metabolic syndrome, fasting glucose, insulin levels, and insulin resistance." (PMID 25549360, 2014). "The aim of the study was to explore the involvement of acyl-CoA synthetase 1 (ACSL1) in bioactive lipid accumulation and the induction of liver insulin resistance (InsR) in animals fed an HFD." (PMID 38613036, 2024).
steatosis (6 papers, 2017 to 2024). Increased lipid within the cytoplasm of cells. "Collectively, we demonstrate that LC alleviates steatosis by reducing acetyl-CoA levels and ER translocation of ACSL1 in human NASH." (PMID 37503004, 2023). "We show that acetyl-CoA accumulation from ketogenic insufficiency induces ER translocation of ACSL1, resulting in fatty acid re-esterification and steatosis." (PMID 37503004, 2023). "Here, we demonstrate that carnitine supplementation attenuates hepatic steatosis under ketogenic insufficiency by alleviating ER translocation of ACSL1." (PMID 37503004, 2023).
type 2 diabetes (5 papers, 2020 to 2024). "A phenome-wide association study of ACSL1 revealed associations with type 2 diabetes, blood glucose, age at menopause, mean platelet volume and mean reticulocyte volume." (PMID 39386187, 2024). "Type 2 diabetes model mice (KK-Ay/TaJcl) were used to investigate the effect of CE on glucose tolerance, ACSL1 expression, and related signal molecules in vivo." (PMID 35869105, 2022). "Here we describe the function of ACSL1 in adipocytes as a molecular target of CE as well as in the amelioration of type 2 diabetes in a mice model in vivo." (PMID 35869105, 2022). "ACSL1 was demonstrated as a molecular target of CE in type 2 diabetes both in a cell culture system and diabetic mouse model." (PMID 35869105, 2022).